PARP1 (poly(ADP-ribose) polymerase 1)
Diseases named in the same sentence as PARP1 in open-access papers (continued):
Sharing a sentence is not in itself a finding about the gene and the disease.
amyotrophic lateral sclerosis (10 papers, 2019 to 2025). Amyotrophic lateral sclerosis (ALS) is a neurodegenerative disease characterized by progressive muscular paralysis reflecting degeneration of motor neurons in the primary motor cortex, corticospinal tracts, brainstem and spinal cord. "For example, a small-molecule inhibitor of nuclear PARP-1/2 activity was developed to treat amyotrophic lateral sclerosis (ALS) by reducing the formation of cytoplasmic TDP-43 aggregates in mammalian cells." (PMID 35585082, 2022). "Aberrant PAR signaling is implicated in numerous neurodegenerative diseases, including Alzheimer, Parkinson, amyotrophic lateral sclerosis, and cerebellar ataxia, where increased PAR levels and PARP1 activity are commonly observed." (PMID 40905723, 2025). "Poly (ADP-ribose)-polymerase-1 (PARP1) is another secreted protein that is differentially expressed in XIST-silenced tissues and is activated in MS and different neurodegenerative diseases, including Huntington’s disease and amyotrophic lateral sclerosis." (PMID 40407589, 2025). "In addition, PARP1 promotes the formation of TDP-43- and FUS-rich granules in the cytoplasm, two RNA-binding proteins which form neuronal cytoplasmic inclusions observed in certain neurodegenerative diseases such as amyotrophic lateral sclerosis and frontotemporal lobar degeneration." (PMID 36497190, 2022).
Chagas disease (10 papers, 2013 to 2023). A parasitic infection caused by Trypanosoma cruzi. "Accordingly, PARP1 inhibition was found to be beneficial for mitochondrial function and left ventricular function in a study that evaluated the role of PARP1 in the maintenance of mtDNA-dependent mitochondrial function in Chagas disease." (PMID 35740913, 2022). "We also determined that PARP1 signals c-Fos- and JunB-mediated AP-1 transcriptional activation of profibrotic gene expression and demonstrated the significance of PARP1 inhibition in controlling chronic fibrosis in Chagas disease." (PMID 33172999, 2020). "We propose that small molecule PARP1 inhibitors offer a potential therapy for controlling the pathologic chronic inflammation in Chagas disease through modulation of the Mφ signaling of cGAS- NF-κB pathway." (PMID 32315358, 2020). "PARP1 depletion was beneficial in arresting the myocardial inflammatory infiltrate through dampening the proinflammatory activation of tissue Mφ in Chagas disease." (PMID 32315358, 2020). "We propose that chemical inhibitors of PARP1 offer a potential therapeutic target in arresting chronic inflammation in Chagas disease through modulation of the macrophage proinflammatory signaling." (PMID 32315358, 2020). "We, therefore, first determined if inhibition of PARP1 would arrest chronic inflammation in Chagas disease." (PMID 32315358, 2020). "We also fractionated the Ev and used a variety of selective inhibitors to determine the role of DNA- and protein-recognizing innate immune receptors in Ev-PARP1 signaling of Mφ response in Chagas disease." (PMID 32315358, 2020). "We surmise that PARP1 is an essential transcriptional regulator that transmits the stimulus provided by Ev produced during Chagas disease to signal the proinflammatory cytokines’ expression." (PMID 32315358, 2020). "We discuss the potential mechanism of PARP1/PAR interference with mitochondrial function in Chagas disease." (PMID 29851986, 2018). "In this study, we aimed to determine the role of PARP1 in mitochondrial health during Chagas disease." (PMID 29851986, 2018). "Further studies will be required to delineate the potential role of nuclear PARP1 in driving chronic inflammation in Chagas disease." (PMID 29851986, 2018). "In this study, we have employed genetic deletion and chemical inhibition approaches to determine the role of PARP1 in maintaining mtDNA dependent mitochondrial function in Chagas disease." (PMID 29851986, 2018). "In summary, we have used in vitro and in vivo models of T. cruzi infection and Chagas disease, and demonstrated that mitochondrial PARP1/PAR disturbs the POLG-dependent mtDNA integrity, and contributes to loss in mitochondrial function." (PMID 29851986, 2018). "Genetic or chemical inhibition of PARP1 was beneficial in improving the mtDNA content, and mitochondrial and left ventricular (LV) function in Chagas disease." (PMID 29851986, 2018). "We, therefore, examined if control of PARP1-dependent mitochondrial impairment and oxidative stress arrested cardiac remodeling and LV dysfunction in Chagas disease." (PMID 29851986, 2018). "We propose that while mitochondrial PARP1 is detrimental to maintaining the mtDNA integrity as observed in this study, nuclear PARP1 contributes to chronic inflammation in Chagas disease." (PMID 29851986, 2018). "Furthermore, these researches showed short-term treatment with cGAS antagonists or PARP1 inhibitors was sufficient to potently suppress TEv-induced cytokines’ expression in macrophages, which offered a potential therapy for controlling Chagas disease." (PMID 36825026, 2023). "The PARP1/NF-κB axis has been described as a proinflammatory pathway in several other situations (for example, in macrophages during Trypanosoma cruzi infection and Chagas disease)." (PMID 36869180, 2023).
Chagas disease (continued). "Whether PARP1–SIRT1 imbalance occurs in human Chagas disease and whether PARP1 inhibitors or SIRT1 agonists will be useful in improving the cardiac outcomes in human Chagas disease remain to be investigated in future studies." (PMID 34178728, 2021). "PARP1 signaling of profibrotic response during T. cruzi infection and Chagas disease." (PMID 33172999, 2020). "Finally, immunohistochemical staining of tissues was done to assess the effect of PARP1 depletion on myocardial Mφ activation status in Chagas disease." (PMID 32315358, 2020). "Our results suggest that mitochondrial transport of PARP1 adversely impacts the mtDNA maintenance by Pol γ replisome, and exacerbates the mitochondrial dysfunction, oxidative stress, and cardiac remodeling in Chagas disease." (PMID 29851986, 2018). "Our findings in the present study show that Parp1 deletion was beneficial in controlling the myocardial inflammatory infiltrate, especially the TNF-α-expressing Mφ, in Chagas disease." (PMID 32315358, 2020). "Oxidized DNA released from Trypanosoma cruzi extracellular vesicles signal the poly(ADP-ribose) polymerase 1 (PARP1)-cGAS-nuclear factor kappa B (NF-κB) pathway for proinflammatory macrophage activation and worsens the chronic inflammatory pathology in Chagas disease." (PMID 35108342, 2022). "Whether TEv also provide antigenic stimulus and PARP1-cGAS induce antigen presenting capacity of the Mφ and support chronic activation of cytotoxic CD8+ T cells that are known to be pathologic in human Chagas disease remains to be determined in future studies." (PMID 32315358, 2020). "We surmise that SIRT/PARP1 balance along with activators of SOD2 will provide promising new therapeutic strategies for arresting chronic oxidative and inflammatory stress and cardiac dysfunction in Chagas disease." (PMID 30044789, 2018). "Likewise, how the crosstalk or substrate allocation between SIRT1 and PARP1 is regulated is not known, and further studies will be needed to understand their precise role in human health and disease, especially as related to Chagas disease." (PMID 34178728, 2021).
colorectal tumor (10 papers, 2019 to 2026). "On the other hand Parp-1, which is also causally linked to DNA repair, protects against colorectal tumor induction." (PMID 33361772, 2020). "Using a CRC mouse model, we further demonstrated that PARP-1 protects against colorectal tumor induction, whereas it promoted colorectal tumor progression driven by intestinal inflammation." (PMID 39456536, 2024). "For example, PARP-1 can protect against colorectal tumor formation and at the same time promoting inflammation-driven progression of these tumors." (PMID 33572586, 2021). "So, in summary, targeting the ferroptosis suppressor PARP1 may sensitize colorectal tumors and improve treatment outcomes." (PMID 41561226, 2026). "They found that hypoxia can induce GSDMD FL to translocate into nucleus of colorectal tumor cells to interact with poly (ADP-ribose) polymerase-1 (PARP-1), which blocks DNA repair function of PARP-1 to accelerate apoptosis." (PMID 38429278, 2024). "OSBPL2 defect supported colorectal tumor growth and metastasis, which were suppressed by the ERK and PARP1 inhibitors SCH772984 and AG14361, respectively." (PMID 38267463, 2024). "PARP1 inhibitors like olaparib and talazoparib, which are used to treat BRCA-mutant cancers, may enhance the efficacy of these DNA-damaging agents against colorectal tumors." (PMID 41561226, 2026). "Briefly, this study illustrates that OSBPL2 defect collaborates with ECM Collagen I to promote colorectal tumor growth and metastasis through two independent pathways and provides the basis for appropriate therapy using ERK and PARP1 inhibitors to treat OSBPL2Low CRC." (PMID 38267463, 2024).
head and neck squamous cell carcinoma (10 papers, 2012 to 2025). A squamous cell carcinoma that arises from any of the following anatomic sites: lip and oral cavity, nasal cavity, paranasal sinuses, pharynx, larynx, and salivary glands. "As yet, comparing with unaltered group, there was lower level of CD8+ T cells in PARP1 altered group in head and neck squamous cell carcinoma." (PMID 34531868, 2021). "We reported that PARP1 inhibitors enhance the therapeutic ratio achieved by radiotherapy by interfering with the replication elongation for the HR-deficient head and neck squamous cell carcinoma (HNSCC) cell lines." (PMID 33003585, 2020). "A recent paper demonstrated that PARP-1 inhibitors sensitized head and neck squamous cell carcinoma cells to APR-246 by inactivation of TrxR and production of ROS48." (PMID 30140002, 2018). "In contrast to this study, we have directly demonstrated evidence that PARP-1 protein and activity is essential for the repair of CDD induced by relatively high-LET protons (RBE = 1.7–1.9) in HeLa and head and neck squamous cell carcinoma cells." (PMID 36902352, 2023). "In head and neck squamous cell carcinoma (HNSCC), studies found that the combination of the epidermal growth factor receptor (EGFR) inhibitor cetuximab and the PARP-1 inhibitor olaparib produces significant synergistic radiosensitizing effects." (PMID 41367875, 2025).
Huntington disease (10 papers, 2015 to 2025). Huntington disease (HD) is a rare neurodegenerative disorder of the central nervous system characterized by unwanted choreatic movements, behavioral and psychiatric disturbances and dementia. "In the human biology context, Huntington disease gene carriers have a significantly reduced incidence of some cancer types, consistent with the success of PARP1 inhibitor drugs in oncology applications." (PMID 40905723, 2025). "While many conditions, such as Alzheimer, Parkinson, ALS, and ataxia, are predominantly characterized by elevated PAR levels and PARP1 overactivation, Huntington disease presents a striking exception, with reduced PAR levels and impaired PARP1 activity." (PMID 40905723, 2025). "Preclinical studies suggest that PARP1 inhibition helps treat AD, PD, and Huntington's disease (HD)." (PMID 33609766, 2021). "In this study, we investigated the neuroprotective effect of Olaparib, an inhibitor of PARP-1, in the mouse model of Huntington’s disease." (PMID 33066292, 2020). "In fact, we have previously shown that, INO-1001, a PARP-1 inhibitor, displays a neuroprotective effect in the R6/2 model of Huntington’s disease (HD)." (PMID 28824383, 2017). "A PARP-1 inhibitor, PJ34, inhibits Aβ-induced neuronal death in AD models, and another PARP-1 inhibitor, INO-1001, has shown neuroprotective effects in a mouse model of human Huntington’s disease." (PMID 40216765, 2025). "In several neurodegenerative diseases, i.e., AD, PD, Huntington's disease, and ALS, PARP1's pathological roles have been established, and the use of PARP1 inhibitors as treatment has shown some promise." (PMID 36438061, 2022). "However, Huntington disease exhibits a unique characteristic: reduced PAR levels and impaired PARP1 activity even in prodromal phase." (PMID 40905723, 2025).
lung adenocarcinoma (10 papers, 2008 to 2025). A carcinoma that arises from the lung and is characterized by the presence of malignant glandular epithelial cells. "Furthermore, in patients with lung adenocarcinoma, a high expression of PARP-1 was associated with poor OS and distant metastasis-free survival." (PMID 39201718, 2024). "Pharmacological inhibition of PARP1 significantly attenuated the metastatic potential of lung adenocarcinoma cells." (PMID 31102368, 2019). "There were several ways of PARP1 enhancing the metastasis of lung adenocarcinoma towards brain: promoting the invasion of lung adenocarcinoma cells, anoikis resistance, exosmosis, and self-updating, as well as regulating cerebral microenvironment." (PMID 29152079, 2017). "Similarly, shRNA experiments targeting PARP-1 inhibited distant metastasis to the bone and brain in a lung adenocarcinoma mouse model." (PMID 39201718, 2024). "Meanwhile, a new study claimed that PARP1 could promote the metastasis and recurrence of lung adenocarcinoma towards brain and bones by regulating several steps in the metastasis process, which was not related to DNA repair." (PMID 29152079, 2017). "It has demonstrated that knockout or inhibition of PARP1 could decrease the migration of lung adenocarcinoma significantly, which indicated PARP1 was involved in the migration of NSCLC." (PMID 29152079, 2017).
medulloblastoma (10 papers, 2010 to 2024). A malignant, invasive embryonal neoplasm arising from the cerebellum. "We introduced single or combined Rad54 and Parp-1 inactivating germline mutations in Ptc1 heterozygous mice, a well-characterized model of medulloblastoma, the most common malignant pediatric brain tumor." (PMID 29254138, 2017). "Interestingly, high PARP1 mRNA expression was associated with poor disease outcome in a gene expression datasets of medulloblastoma, posterior fossa ependymoma and pediatric HGG, with high significance in the latter." (PMID 22184287, 2011). "PARP-1 expression was high in D425Gil tumors, consistent with a previous study showing high expression in D283 medulloblastoma cells and clinical samples, although this expression remained high in groups treated with veliparib." (PMID 33996894, 2021). "Veliparib, a small molecule inhibitor of PARP1/2, was assessed for its ability to inhibit DNA repair in two human medulloblastoma cell lines." (PMID 33996894, 2021). "Increased PARP1 expression has been reported in paediatric high-grade astrocytomas, medulloblastoma, and ependymoma." (PMID 28654422, 2017). "In this study a significant radiation sensitizing effect of treatment with the PARP1 inhibitor Olaparib was demonstrated in medulloblastoma, HGG and ependymoma cell lines." (PMID 22184287, 2011). "In all cell lines PARP1 protein expression was detected, in particular in ependymoma cell line Res196 and medulloblastoma cell line D283-med." (PMID 22184287, 2011). "In medulloblastoma a more varied staining pattern was found, with a higher number of sections showing moderate nuclear PARP1 staining." (PMID 22184287, 2011). "The PARP1 expression was significantly higher in pediatric ependymoma and medulloblastoma, compared to cortex and cerebellum, while PARP1 expression in HGG was significantly higher compared to normal cortex." (PMID 22184287, 2011). "In addition, PARP1 protein expression was found in medulloblastoma patients including cell lines." (PMID 22184287, 2011). "In order to study the effect of PARP1 inhibition on the induction and persistence of DSBs in ependymoma, HGG and medulloblastoma cells, the presence of γH2AX foci was assessed by immunofluorescence." (PMID 22184287, 2011). "Interestingly, we observed higher PARP1 and CHK1 expression in SHH-MB tissues compared to normal cerebellum in humans and in Ptch−/− mice as well as in a Ptch−/− medulloblastoma primary cultures (N-MB)." (PMID 34508175, 2021). "Medulloblastoma and HGG are more variable but overall also highly express PARP1." (PMID 22184287, 2011). "Increased PARP1 expression was observed in medulloblastoma, ependymoma and HGG, as compared to non-neoplastic brain tissue." (PMID 22184287, 2011).